IGF1 (insulin like growth factor 1)
Diseases named in the same sentence as IGF1 in open-access papers (continued):
Sharing a sentence is not in itself a finding about the gene and the disease.
Obesity (continued). "In that study, the significance of the univariate relationship between lower IGF-1 levels and a higher risk for incident frailty was lost after adjusting for age, sex, medication, obesity, physical activity, and chronic disease." (PMID 28609827, 2017). "IGF-1 is a growth factor that is secreted by the liver and is commonly associated with obesity and hyperinsulinism." (PMID 28261315, 2017). "Recently, low levels of adiponectin have been associated with an increased risk of obesity-related cancers and development of more aggressive phenotype, with concomitant alterations in the bioavailability of IGF-1." (PMID 29036907, 2017). "Accumulating evidence from clinical and animal studies suggests that obesity-associated molecules including leptin, insulin, IGF-1, and adiponectin influence the development of colonic diseases." (PMID 28170448, 2017). "Recent epidemiological studies provided evidence that insulin, GH/IGF-1, and adiponectin signaling are molecular pathways interconnected with each other and linking obesity to metabolic diseases risk." (PMID 29036907, 2017). "Obesity and acromegaly are deleterious conditions, associated with high insulin and IGF1 levels, and decreased life expectancy." (PMID 28316059, 2017). "Low grade inflammation and changes in microbiota are associated with obesity and have been discussed as possible causes, along with insulin-like growth factor-1 and leptin." (PMID 28804436, 2017). "Two of the 15 top KDs, namely HMGCR and IGF1, were previously identified as signals of genome-wide significance for obesity, lipids and T2D, all risk factors of CVD." (PMID 28957322, 2017). "Impairment of GH/IGF-1 axis seems to be associated to the risk of the development of sarcopenic obesity and ectopic fat deposition in the liver." (PMID 26741958, 2016). "Further studies are required to clarify the pathogenic mechanisms underlying the involvement of IGF-1 in obesity-related nephropathy." (PMID 27138941, 2016). "In conclusion, our findings demonstrate that a low IGF-1 serum level is associated to obesity related glomerular lesion in morbidly obese patients." (PMID 27138941, 2016). "An increase in the IGF-1 level after weight loss has been demonstrated, suggesting that obesity-related IGF-1 deficiency is an acquired condition." (PMID 27138941, 2016). "One of the mechanisms proposed to explain the association between obesity and cancer risk is the potential action of adipokines (e.g., leptin, adiponectin, insulin growth factor-1 (IGF-1)) on tumor tissue." (PMID 25857300, 2015). "In particular, our results suggest that there is a stronger association of the IGF1 signature genes with 70 BC rGSSs, than for the obesity-associated signature." (PMID 26100469, 2015). "At present, the following three proposed mechanisms exist which aim to explain the association between obesity and aggressive PCa: The insulin/insulin-like growth factor-1 axis, the action of sex hormones and adipokine signaling." (PMID 25663903, 2015). "Obesity leads to decreased level of circulating adiponectin and increased level of insulin-like growth factor 1 and leptin, which contribute to an increased risk of colorectal cancer." (PMID 26467912, 2015). "On the other hand, our method identifies many dozen genes of MAPK signalling pathway which have not been considered as a common BC signature in context of their functional association of obesity, IGF1 pathway and BC." (PMID 26100469, 2015). "Similar to the obesity-associated tGSS, our results indicated that genes belonging to the IGF1-tGSS are generally found to co-occur in more rGSSs than expected from random simulations." (PMID 26100469, 2015). "Obesity, loss of muscle mass, and decreased IGF-1 levels are independently associated with disability and frailty in elderly subjects." (PMID 26457580, 2015). "On the other hand, genes in either the obesity or IGF1-associated tGSSs that occur in three or less rGSSs are termed SN gIDs." (PMID 26100469, 2015).
Obesity (continued). "In particular, our analysis suggests a close association of many genes expressed in MAPK pathways with obesity, IGF1 and BC pathways." (PMID 26100469, 2015). "Practically, our results suggest that there is a stronger association of the IGF1 signature genes with the 70 BC rGSSs, than for the obesity-associated signature." (PMID 26100469, 2015). "Our method allows us to quantify a measure of associations between obesity, IGF1 pathway and BC signatures, as well as predict potentially SC and SN therapeutic target genes." (PMID 26100469, 2015). "With respect to IGF-1, several studies conducted among postmenopausal White women have reported an inverted U-shaped association with obesity." (PMID 26352264, 2015). "In contrast, while we showed slight association between the obesity-associated gene signature with the rGSSs, this association appear to be weaker when compared to that of the IGF1 signaling pathway." (PMID 26100469, 2015). "hNAG-1 increases oxidative metabolism, lower obesity and decrease the insulin/IGF-1 pathway, all of which are associated with survival and longevity." (PMID 25239873, 2014). "There are evidences of benefits of physical exercise to normalize obesity-altered lipid patterns, improve glucose metabolism, change the growth hormone/IGF-1 axis, and consequently reduce the risk of obesity-associated comorbidities." (PMID 24829560, 2014). "Aside from mechanical stress, increased circulating levels of obesity-associated hormones, such as sex steroids, insulin, insulin-like growth factor 1, and leptin, are potential pathogenic mediators in obesity-associated lumbar disc degeneration (LDD)." (PMID 24441571, 2014). "Obesity is associated with decreased GH secretion and IGF-1 deficiency is associated with increased abdominal adipose tissue accumulation, decreased BMD, and increased fracture risk as demonstrated by ours and other groups." (PMID 24963291, 2014). "Future studies will involve examining the role of obesity in mice that are deficient in IGF-1 to determine the IGF-1-dependence of energy balance effects on colon tumor development." (PMID 24732966, 2014). "The mitogenic and anti-apoptotic environment caused by elevated levels of insulin and IGF-1 in obesity accelerates the stepwise accumulation of mutations and, hence, favor carcinogenesis." (PMID 24829560, 2014). "Obesity is strongly associated with insulin resistance, in which the levels of insulin and IGF-1 are elevated." (PMID 23304125, 2012). "The current review discusses the role of insulin and insulin-like growth factor-1/FoxO-mediated transcription for the pathogenesis of obesity-associated dementia from model organisms to humans." (PMID 22654904, 2012). "Surprisingly, high-fat diet specifically reduces the expression of FoxO3a and FoxO6 suggesting that IR/IGF-1 → FoxO-mediated transcription is involved in the pathogenesis of obesity-associated cognitive impairment." (PMID 22654904, 2012). "Obesity, in turn, impacts levels of serum estrogen, insulin, and/or insulin-like growth factor-1, which have all been implicated as possible links between obesity and breast cancer." (PMID 18162139, 2007). "Abnormalities in the IGF-1 axis may be associated with the development of obesity, which in turn may affect metabolic health." (PMID 40538800, 2025). "Furthermore, obesity is often associated with hyperinsulinemia, with high levels of insulin and insulin-like growth factor 1 (IGF-1), a pro-tumorigenic hormone, aiding in the development of cancer." (PMID 40722609, 2025). "IGF-1 is traditionally used in children to diagnose growth hormone deficiency, but IGF-1 concentrations may also change in other metabolic states such as obesity." (PMID 39899498, 2025). "The association between diabetes and increased EC risk may involve multiple intricate mechanisms, including obesity, hyperglycemia, hyperinsulinemia, activation of the Insulin-like Growth Factor-1 (IGF-1) pathway, and elevated levels of inflammatory cytokines." (PMID 40636107, 2025).
Obesity (continued). "Moreover, the positive energy balance associated with obesity induces a variety of metabolic factors such as insulin and insulin-like growth factor-1, which alter the nutritional milieu and create an environment conducive to tumor initiation and progression." (PMID 40904778, 2025). "Increased levels of leptin and IGF-1 may serve as potential plasma biomarkers of elevated fetal adiposity, which can predispose individuals to infant obesity and metabolic dysfunction later in life." (PMID 40725173, 2025). "Their findings revealed that obesity is associated with significant alterations in the miRNA cargo of small EVs, particularly miRNAs targeting inflammatory and anabolic signaling pathways such as Wnt/β-catenin, IGF-1, and PI3K/AKT." (PMID 41150813, 2025). "In addition, other hormonal factors associated with obesity, including insulin-like growth factor 1(IGF-1), steroid hormones, AMP-activated protein kinase, and leptin, also play a significant role in the initiation and progression of BC." (PMID 40136371, 2025). "Recent studies suggest that chronic low-grade inflammation caused by obesity may promote the calcification of spinal ligaments, while elevated levels of IGF-1 may accelerate the ossification process by enhancing bone formation and tissue proliferation." (PMID 40535334, 2025). "Obesity is associated with hyperinsulinemia and increased levels of free IGF-1." (PMID 40565082, 2025). "The insulin/IGF-1 signaling is implicated in regulating fetal growth, T-cell maturation, linear growth, and the development of conditions such as acne, atherosclerosis, diabetes mellitus, obesity, and cancer." (PMID 40357063, 2025). "As we also found higher IGF-1 concentrations in fatter compared to leaner cats, we speculate that this could be related to systemic alterations associated with overweight/obesity, for example alterations of the insulin-IGF axis." (PMID 40001060, 2025). "Obesity-associated hyperactivation of the insulin/Insulin-like Growth Factor 1 (IGF-1) signaling pathway further facilitates tumor cell energy metabolic reprogramming and protein synthesis through the mTORC1 pathway, thereby providing the bioenergetic foundation for liver metastasis." (PMID 41164182, 2025). "Metabolic and hormonal disorders and chronic inflammation associated with obesity may be linked with increased levels of the Insulin-like Growth Factor 1 (IGF-1), and promote the induction of carcinogenesis." (PMID 40634443, 2025). "The proposed hypotheses underlining excessive adiposity and gastrointestinal cancer risks include altered insulin and IGF-1 signaling, chronic low-grade inflammation associated with obesity, and disruptions in sex hormone metabolism." (PMID 39335195, 2024). "Interestingly, in the last decade, studies have revealed an association between subnormal insulin-like growth factor-1 (IGF-1) levels and various MetS components, including obesity, dyslipidaemia, IR and hyperglycaemia." (PMID 38542217, 2024). "A German study found that children with obesity showed higher growth at birth than their normal-weight counterparts and had an accelerated growth rate thereafter, which was associated with increased levels of IGF-1, insulin, and leptin in these children." (PMID 38398863, 2024). "Pediatric reports have a controversy concerning the association between IGF-1 values and obesity." (PMID 39438878, 2024). "Extensive previous studies have suggested that certain bioactive components in breast milk, such as leptin, adiponectin, and insulin-like growth factor-1, may play important roles in reducing the risk of offspring overweight/obesity." (PMID 38732598, 2024). "However, the drug Mecasermin targeting IGFBP1 has been approved to treat growth failure in pediatric patients with primary IGF-1 deficiency or with growth hormone gene deletion and is likely to be used for treating obesity." (PMID 38614964, 2024).
Obesity (continued). "We will look at topics such as neonatal anthropometry, thyroid issues, adrenal problems, hypogonadism, bone metabolism abnormalities, metabolic syndrome resulting from severe obesity caused by hyperphagia, deficiencies in the GH/IGF-1 axis, and the corresponding responses to treatment." (PMID 38737552, 2024). "Circulating insulin-like growth factor-1 (IGF-1) is positively associated with the risk of BC recurrence, and is more frequently dysregulated in older people, especially in those with metabolic syndrome (MetS) and obesity." (PMID 37106164, 2023). "This means that high GS (and possibly elevated circulating IGF1) combined with low levels of vitamin D could serve as a risk factor for obesity, especially as the association between hypovitaminosis D and obesity is well established." (PMID 37892272, 2023). "Furthermore, obesity with prediabetes is associated with changes in IGF-1 signaling and acts on PI3K/Akt/GSK3β/β-catenin signaling, which results in rapid cell proliferation and development of breast tumors in obese rats than the lean rats." (PMID 37511200, 2023). "Moreover, insulin and IGF-1 stimulate protein synthesis in the skeletal muscles of mice, and impaired insulin activity in skeletal muscles is linked to obesity and sarcopenia." (PMID 37237929, 2023). "In this context, VLCKD may represent a preventive measure in postmenopausal women with obesity, to reduce visceral adipose tissue, inflammatory status, growth factors such as insulin and IGF-1, and to reduce the risk of endometrial cancer." (PMID 37405618, 2023). "These trials will not only help determine the safety and efficacy of GH and IGF-1 therapy in humans but also provide more accurate information on the potential benefits and risks associated with these interventions in the context of obesity management." (PMID 37298507, 2023). "A recent study on an in vitro and in vivo mouse model of obesity has confirmed the relationship between obesity, AT-specific IGF-1, macrophage-associated AT inflammation and polarization of TAMs to M2 phenotype, as potential drivers of CRC development in women deprived of ovarian hormones." (PMID 36835075, 2023). "The complex interplay between these hormones and growth, as well as their roles in regulating energy balance and body composition, suggest that modulating GH and IGF-1 levels may be a promising strategy for combating obesity and its associated comorbidities." (PMID 37298507, 2023). "Moreover, obesity is associated with increased levels of circulating IGF1, also secreted by ASCs/MSCs." (PMID 36010901, 2022). "Furthermore, obesity is associated with a reduced secretion of Growth Hormone (GH) with consequent reduced secretion of Insulin-like Growth Factor-1 (IGF1) from the liver." (PMID 36557260, 2022). "Indeed, the hormone insulin and its structural relation, insulin-like growth factor 1 (IGF-1), have been linked to both carcinogenesis and obesity." (PMID 36038791, 2022). "Other cytokines that may play a causative role in carcinogenesis in the state of obesity include insulin-like growth factor-1 (IGF-1), transforming growth factor-beta (TGF-β), and vascular endothelium growth factor." (PMID 35892738, 2022). "Notably, both adiponectin and IGF-1 displayed directionally opposite associations with upper-body fat distribution compared to obesity in females." (PMID 36558416, 2022). "IGF-2 is raised in circulation in human obesity and reduced after weight loss and can increase cellular proliferation through the insulin receptor, at least in 3T3-like fibroblasts generated from mouse embryos nullizygous for IGF-1 and IGF-1R." (PMID 36038791, 2022). "Based on our findings, the authors speculate that in the crosstalk between PCOS, NAFLD, IR, and obesity, IGF1 might act as a linker and be a pathogenic factor for developing PCOS." (PMID 35605922, 2022).
Obesity (continued). "Obesity is associated with increased concentration of testosterone in females, which leads to promotion and proliferation of cells along with local production of insulin-like growth factor-1." (PMID 35419231, 2022). "In addition, it has been established that obesity is associated with higher free IGF‐1 levels, and there is evidence from the Long Life Family Study of a nonlinear relationship between IGF‐1 levels and BMI." (PMID 34363732, 2021). "The maintenance DNA methyltransferase DNMT1 via CpG promoter methylation epigenetically controls the expression of important developmental genes involved in mTORC1 signaling including insulin (INS), IGF-1 (IGF1), and fat mass- and obesity-associated gene FTO (FTO)." (PMID 33494388, 2021). "Moreover, free IGF-1 levels are reduced in obesity and IGF-1 concentration was an independent factor associated with IR." (PMID 33562271, 2021). "Metabolic risk factors such as MetS, obesity, diabetes or acromegaly, both hyperglycemia, chronic hyperinsulinemia and an increase in local expression and/or serous concentrations of IGF-1 all can play an important role in the mechanisms of colon carcinogenesis." (PMID 34208601, 2021). "An early development of overweight and obesity and higher concentrations of IGF-1 at 2.5 years of age have been associated with an excessive amount of protein intake, and some studies have shown that children who consumed YCF had a lower protein intake than those who consumed cow’s milk." (PMID 34684413, 2021). "Increased concentration of IGF-1 in the mother may cause excessive growth of adipose tissue in the foetus and, consequently, the occurrence of obesity in later life." (PMID 34371854, 2021). "Weight gain during childhood promoted by excess protein intake is the result of increased insulin-hyper aminoacidemia levels which, in turn, stimulates IGF-1 secretion, increasing later risks concerning obesity and associated diseases, reinforcing the requirement for strict IFs protein adjustments." (PMID 34836188, 2021). "The reasons behind the poor treatment outcome are not fully understood; however, obesity is associated with the systemic elevation of insulin-like growth factor 1 (IGF-1), adipokines, cytokines, and pro-angiogenic factors, which create a pro-oncogenic environment." (PMID 32899433, 2020). "Based on the evidence, the increased leptin, IGF-1, and sex hormone levels might be implicated in accelerated skeletal maturation in obesity." (PMID 32988365, 2020). "IGF-1 has an important role in infant growth where the high concentration of IGF-1 in the human milk promotes rapid growth to the infants that may be associated with overweight and obesity in later life." (PMID 31174304, 2019). "Obesity at a young age causes the delayed onset of puberty and may result in the lower lifetime exposure of insulin-like growth factor 1 (IGF-I), which may affect the development of prostate cancer later in life." (PMID 30736371, 2019). "Moreover, obesity and high levels of insulin and IGF-1, as well as having diabetes mellitus are associated with worse survival in cancer." (PMID 31113478, 2019). "A previous study has suggested that milk intake associated with risk of childhood obesity, and the insulinotropic and IGF-1-raising effects of milk and dairy products may have further adverse effects on obesity." (PMID 29996840, 2018). "Other implicated factors could be hyperinsulinemia related to obesity, leading to higher bioavailable free insulin-like growth factor-1 (IGF1) levels, which, in turn, would favor tumor formation and progression." (PMID 30224918, 2018). "However, further comprehensive studies will be needed to establish the contribution of the obesity-associated leptin-IGF1/IGBP3 axis in intestinal stem cell biology and decipher the causal or correlational link among these pathways." (PMID 30250849, 2018).